GPR19 (G protein-coupled receptor 19)
Description:
G protein-coupled receptor that plays a role in the regulation of circadian rhythms and energy metabolism. Participates in maintaining proper circadian gene expression in the suprachiasmatic nucleus (SCN), the locus of the master circadian clock in the brain (By similarity). May function as a coordinator of aging-associated metabolic dysfunction, stress response, DNA integrity management, and eventual senescence. Upon binding to adropin, modulates mitochondrial energy metabolism via the p44/42-PDK4 signaling pathway, influencing pyruvate dehydrogenase activity (By similarity).
Tractability: Small molecule: it belongs to a druggable protein family. Antibody: UniProt places it where antibodies can reach, with high confidence; its Gene Ontology location is reachable by antibodies, with high confidence; UniProt predicts a signal peptide or a membrane-spanning region.
Target class: Family A G protein-coupled receptor; Membrane receptor
Gene: Protein-coding gene on chromosome 12 (12,660,047 to 12,696,705, reverse strand). Ensembl gene ENSG00000183150.
Subcellular location: Cell membrane
Gene Ontology:
Molecular function: G protein-coupled receptor activity; protein binding
Biological process: G protein-coupled receptor signaling pathway
Cellular component: cilium; plasma membrane; membrane
Genetic constraint (gnomAD): Loss-of-function variants: 14 observed, 29.75 expected, observed/expected ratio (o/e) 0.47, 90% interval 0.31 to 0.74. The upper end of that interval is the gene's LOEUF score, 0.74, which puts it in group 3 of 6, group 1 being the genes least tolerant of losing a copy. Missense variants: 402 observed, 524.11 expected, observed/expected ratio (o/e) 0.77, 90% interval 0.71 to 0.83. Synonymous variants: 168 observed, 192.2 expected, observed/expected ratio (o/e) 0.87, 90% interval 0.77 to 0.99.
Homologues: Orthologues: chimpanzee GPR19 (98% identical), macaque GPR19 (97% identical), guinea pig GPR19 (93% identical), rabbit GPR19 (92% identical), dog GPR19 (92% identical), mouse Gpr19 (89% identical), pig GPR19 (89% identical), rat Gpr19 (88% identical), tropical clawed frog gpr19 (70% identical), zebrafish gpr19 (63% identical). Paralogues in human: GPR83 (22% identical), NPY2R (20% identical), MCHR1 (18% identical), MCHR2 (18% identical), TACR1 (18% identical), TACR3 (17% identical), NPY1R (17% identical), TACR2 (17% identical), PRLHR (16% identical), MTNR1A (16% identical), MTNR1B (15% identical), PROKR1 (15% identical), and 21 more.
Diseases named in the same sentence as GPR19 in open-access papers:
GPR19 is named in the same sentence as 37 diseases in open-access papers, as found by Europe PMC text mining. Sharing a sentence is not in itself a finding about the gene and the disease. The quoted sentences say what the papers report.
breast carcinoma (10 papers, 2020 to 2025). "Furthermore, overexpression of GPR19 in breast cancer cells was linked to regaining the tumor cells to epithelial characteristics by expressing E-cadherin, which facilitates metastatic colonization of the tumor." (PMID 39337311, 2024). "Elegantly reinforcing the molecular relevance of MDC1-PHB to the activity of GPR19, we found that this cohort of in silico-derived proteins interacts with each other to create a network of interconnected signaling functions linked to breast cancer, aging, and DDR." (PMID 37239845, 2023). "In mesenchymal-like breast cancer, for example, overexpression of GPR19 stimulates E-Cadherin expression and induces an epithelial-like phenotype via the MAPK/ERK1/2 pathway, thereby contributing to carcinogenesis and metastasis." (PMID 40647442, 2025). "At the 2 μg expression level of GPR19, the presentation of breast cancer, metabolic, and circadian rhythm functions were seen." (PMID 37239845, 2023). "It is interesting to note that for breast cancer cell lines, GPR19 demonstrates differential expression levels that are associated with differing degrees of metastatic capacity." (PMID 37239845, 2023). "The involvement of adropin and its putative receptor, G-protein coupled receptor 19 (GPR19), on tumor cell is only studied in human breast carcinoma." (PMID 37904094, 2023). "GPR19 facilitates breast cancer cell metastasis by contributing to the promotion of mesenchymal to epithelial transition." (PMID 36362387, 2022). "Overexpression, or ligand (adropin) activation, of GPR19, was shown to induce mesenchymal-like breast cancer cells to adopt an epithelial-like phenotype." (PMID 36362387, 2022). "In other tumour entities, including papillary thyroid carcinomas, gastrointestinal stromal tumours, pancreatic adenocarcinomas, urinary bladder cancer, and breast cancer, we found single tumours, probably representing specific tumour subgroups, with medium–high GPR19 expression." (PMID 37923782, 2023). "Adropin’s action on GPR19 initiates MET in mesenchymal like breast cancer cells." (PMID 37904094, 2023). "Gpr19 has been shown to be expressed in melanoma, lung cancer, and breast cancer cells." (PMID 34789778, 2021). "Moreover, it was found that adropin modulates E-cadherin expression in breast cancer cells via activation of GPR19." (PMID 32012786, 2020). "Furthermore, overexpression of GPR19 in mesenchymal-like breast cancer stimulates E-cadherin expression and promotes the epithelial-like phenotype via the MAPK/ERK1/2 pathway." (PMID 32012786, 2020). "Adropin is an endogenous ligand for GPR19 and adropin-mediated activation of GPR19 stimulates the intracellular MAPK/ERK1/2 signaling pathway, which is essential for the upregulation of E-cadherin and accompanying phenotypic changes in human breast cancer cells." (PMID 33133015, 2020).
lung carcinoma (3 papers, 2016 to 2022). "In lung cancer cells, the expression of GPR19 has a potential supporting role in G2-M cell cycle progression, and in metastatic melanoma, an increased expression of GPR19 was observed." (PMID 36362387, 2022).
metastatic melanoma (3 papers, 2008 to 2023). A melanoma that has spread from its primary site to another anatomic site. "Overall, our findings support the results of previous studies showing elevated GPR19 mRNA expression in metastatic melanomas, glioblastomas, SCLC, and breast cancer." (PMID 37923782, 2023). "In contrast, the metastatic melanomas express higher levels of genes such as MAGE, GPR19, BCL2A1, MMP14, SOX5, BUB1, RGS20, and more." (PMID 18442402, 2008). "Based on gene microarray analysis and other molecular techniques, GPR19 was identified among a group of genes with higher expression in metastatic melanoma samples compared with primary non-metastatic cutaneous cancers." (PMID 37923782, 2023).
adrenal carcinoma (2 papers, 2020 to 2024). A carcinoma involving a adrenal gland. "According to GEPIA and NCBI data, expression of GPR19 in normal adrenal gland is relatively low, but it' s strongly rising in adrenal carcinoma (0.37 in normal adrenal vs. 9.69 in adrenal carcinoma according to GEPIA)." (PMID 33133015, 2020). "In a previous study, we evaluated the effect of adropin on adrenal cancer cell lines (HAC15) and its receptor (GPR19) expression in adrenal tumor samples." (PMID 39201370, 2024).
Glucose intolerance (2 papers, 2023 to 2025). Glucose intolerance (GI) can be defined as dysglycemia that comprises both prediabetes and diabetes. "As such, GPR19 has been studied in the context for metabolic syndromes as well, where its absence leads to glucose intolerance and cardiac dysfunction." (PMID 39897058, 2025). "However, only male GPR19 KO mice display glucose intolerance in response to a high fat diet." (PMID 37061564, 2023).
small cell lung carcinoma (2 papers, 2021 to 2023). Small cell lung cancer (SCLC) is a highly aggressive malignant neoplasm, accounting for 10-15% of lung cancer cases, characterized byrapid growth, and early metastasis. "Among the 30 different tumour entities investigated, strong GPR19 expression was found in adenocarcinomas, typical and atypical carcinoids of the lung, and small cell lung cancer." (PMID 37923782, 2023).
adrenocortical carcinoma (1 paper, 2020). "Considering the stimulatory roles of adropin on HAC15 cell proliferation, we can assume that elevated expression of the GPR19 may indirectly cause a speed-up rate of proliferation in adrenocortical carcinoma." (PMID 33133015, 2020). "According to the GEPIA data and our results, the expression of GPR19 was significantly elevated in adrenocortical carcinoma in relation to normal adrenal." (PMID 33133015, 2020). "We have also demonstrated that expression of GPR19 is elevated in adrenocortical carcinoma in relation to normal adrenal glands." (PMID 33133015, 2020). "Expression of GPR19 was significantly increased in adrenocortical carcinoma, which is in line with previously reported GEIPA data." (PMID 33133015, 2020). "Due to the significant stimulatory role of the adropin-GPR19 system in the proliferation of human derived adrenocortical carcinoma cell line (HAC15), mediated by ERK1/2 and AKT dependent mechanism, we undertook the analysis regarding the clinical significance of the obtained results." (PMID 33133015, 2020). "Finally, the clinical significance of the obtained results was verified by analysis of ENHO and GPR19 gene expression in human normal adrenals in relation to adrenocortical carcinoma." (PMID 33133015, 2020). "GPR19 expression was elevated in human adrenocortical carcinoma in relation to normal adrenals." (PMID 33133015, 2020). "High level of GPR19 expression in adrenocortical carcinoma may constitute a negative prognostic factor of disease progression." (PMID 33133015, 2020). "Increased expression of GPR19 leads to a statistically significant decrease in survival, suggesting that high expression of GPR19 could constitute a negative prognostic factor of adrenocortical carcinoma disease progression, however this aspect require further studies." (PMID 33133015, 2020).
atherosclerosis (1 paper, 2018). A disease characterized by the build-up of fatty material and calcium deposition in the arterial wall resulting in partial or complete occlusion of the arterial lumen. "The reason why adropin exerts multiple effects in all three vascular cells that participate in the pathogenesis of atherosclerosis could be explained by the possible presence of adropin’s own receptors, other than GPR19, in these cells." (PMID 29701665, 2018).
autism (1 paper, 2025). Persistent deficits in social interaction and communication and interaction as well as a markedly restricted repertoire of activity and interest as well as repetitive patterns of behavior. "Genes reported as potential blood biomarkers of mental health, such as PACSIN1 and SPTBN1 (associated with addiction-related behavior), GPR19 (associated with depression), and AUTS2 (associated with autism), were highlighted in the STRING analysis of this study." (PMID 40917096, 2025).
Bardet-Biedl syndrome (1 paper, 2022). A ciliopathy with multisystem involvement. "Interestingly, we find that two additional ciliary G protein-coupled receptors (Gpr161 and Gpr19) abnormally accumulate in cilia on Bardet-Biedl syndrome neurons." (PMID 36699005, 2022).
glioblastoma (1 paper, 2023). The most malignant astrocytic tumor (WHO grade IV). "GPR19 was also found in a set of genes with high expression in stem cell-like glioblastoma cells." (PMID 37923782, 2023).
medullary thyroid carcinomas (1 paper, 2023). "Besides, noticeable GPR19 expression with average mean IRS values ≥ 3 was observed in only a few tumour entities, including medullary thyroid carcinomas, parathyroid adenomas, and pheochromocytomas." (PMID 37923782, 2023).
myocardial infarction (1 paper, 2015). Gross necrosis of the myocardium, as a result of interruption of the blood supply to the area, as in coronary thrombosis. "The two other associated SNPs in the AA group, rs2270451 (P = 0.024) and rs2301523 (P = 0.039), are located in the 2-Kb upstream sequence of GPR19 (G protein-coupled receptor 19) and within the non-protein coding RNA MIAT (myocardial infarction associated transcript), respectively." (PMID 26236334, 2015).
neuroendocrine tumour (1 paper, 2023). "Overall, our results indicate that in adenocarcinomas and neuroendocrine tumours of the lung GPR19 may serve as a suitable diagnostic or therapeutic target." (PMID 37923782, 2023).
neuroendocrine tumours of the lung (1 paper, 2023). "In adenocarcinomas and neuroendocrine tumours of the lung, GPR19 may serve as a suitable diagnostic or therapeutic target." (PMID 37923782, 2023).
Obesity (1 paper, 2023). Accumulation of substantial excess body fat. "Together, these data suggest that the loss of GPR19 expression attenuates whole-body glucose clearance in diet-induced obesity in a sex-dependent manner." (PMID 37061564, 2023). "Our results suggest that GPR19 deficiency impairs whole-body metabolism in a sex-dependent manner, and may serve a central role in the development of obesity-related metabolic dysfunction." (PMID 37061564, 2023). "In this study, we demonstrate for the first time a role for the orphan G-protein coupled receptor, GPR19, in the regulation of systemic metabolic homeostasis in diet-induced obesity." (PMID 37061564, 2023). "In summary, our study provides robust evidence that GPR19 is a potential regulator of metabolic homeostasis in diet-induced obesity, and thus highlights this GPCR as a possible target for therapeutic applications in the progression of metabolic-associated diseases." (PMID 37061564, 2023).
pancreatic neuroendocrine neoplasm (1 paper, 2023). A neoplasm with neuroendocrine differentiation that arises from the pancreas. "High GPR19 expression was also found in single pancreatic neuroendocrine neoplasms, probably representing a rare subpopulation of these tumours." (PMID 37923782, 2023).
prostate carcinoma (1 paper, 2016). A carcinoma that arises from epithelial cells of the prostate gland. "We found that lncRNA MALAT1 also acted as miRNA sponge to weaken the inhibition of GPR19 expression, they were bound by miR-30d, and the miRNA was a prostate cancer-related miRNA." (PMID 27528026, 2016).
skin tumors (1 paper, 2020). "In this study, we have examined the expression profiles of the pH-GPCRs GPR4 (GPR19), TDAG8 (GPR65), OGR1 (GPR68) and G2A (GPR132) on different types of common skin tumors, SCC, MM, NCN and BCC." (PMID 32948783, 2020).
cancer (6 papers, 2020 to 2023). A tumor composed of atypical neoplastic, often pleomorphic cells that invade other tissues. "GPR19 signaling has been associated with multiple activities linked to dysfunctional aging, e.g., cell cycle control, cancer metastasis, adipocyte proliferation and lipid metabolism, stress-associated apoptosis, mitochondrial function, and diabetes." (PMID 36362387, 2022). "Thus, the potent DDR/Aging/Cancer component of the GPR19 molecular signature also appears to be tightly linked to classical energy management pathways—again reinforcing the potential key status of GPR19 in pathological aging paradigms." (PMID 37239845, 2023). "It has been shown that increases in GPR19 expression are found in cancer cells of various lineages, e.g., lung, breast, adrenals, and pancreas." (PMID 37239845, 2023). "It was further observed that the physical mapping of GPR19 on the chromosome was frequently rearranged in cancer cells." (PMID 36362387, 2022). "According GEPIA (Gene Expression Profiling Interactive Analysis) web server for cancer and normal gene expression profiling based on RNA-seq data, expression of GPR19 in normal human organs is the highest in brain and testis." (PMID 33133015, 2020). "Apart from its physiological functions, GPR19 may play a role in the development and progression of certain cancers, because GPR19 increases cell proliferation and decreases apoptosis." (PMID 37923782, 2023). "While there is data on GPR19 mRNA expression, there appears to be no information on the expression of GPR19 at the protein level in normal and neoplastic tissues or cancer cell lines." (PMID 37923782, 2023).
tumor (5 papers, 2022 to 2024). "A few studies have linked elevated GPR19 expression to tumor progression and metastasis, with these downstream signaling cascades affecting mitochondrial homeostasis." (PMID 37061564, 2023). "We then determined the expression profile for GPR19 for normal human tissues and a wide range of human tumours using a large panel of formalin-fixed, paraffin-embedded, normal and neoplastic human tissue samples." (PMID 37923782, 2023). "This is supported by the negative correlation between GPR19 expression and the expression of the proliferation marker Ki-67 and by the better outcomes of patients with GPR19-positive tumours." (PMID 37923782, 2023). "G-protein coupled receptor 19 (GPR19) is a poorly characterized class A GPCR which has been implicated in the regulation of circadian rhythm, tumor metastasis, and mitochondrial homeostasis." (PMID 37061564, 2023). "As can be seen from the minimum and maximum Immunoreactivity Score (IRS) values assigned to the individual tumours within the different tumour entities, GPR19 expression displayed substantial inter- but also intra-individual variability." (PMID 37923782, 2023). "GPR19, as an adropin receptor, is widely expressed by tumor cells." (PMID 37904094, 2023). "It is possible that all these tumours express GPR19 because the cells and tissues of origin have this receptor; however, lung tumours may lose GPR19 expression with increasing malignancy." (PMID 37923782, 2023). "Elevated GPR19 transcription in CRC tissues was observed, and GPR9 had higher transcription in tumors than in para-tumor tissues." (PMID 37904094, 2023). "In conclusion, adropin/GPR19 is involved in CRC progression, and variations of adropin expression in tumor nest or stroma cells have differently clinic relevance." (PMID 37904094, 2023). "Strong staining was often observed only in small areas of the tumours, with large regions of the samples lacking GPR19, resulting in a low overall score." (PMID 37923782, 2023). "Cluster 1 was characterized by upregulation of tumor-suppressing genes: HNF1B, CCNDBP1, PATJ, EPB41L3, MARVELD2, PTEN in conjunction with cell-cycle genes – GSPT1, GPR19, EAPP, KIT, CDKL1, and stem cell markers – RBBP5, NANOG, NCSTN, ERG, including quiescent stem cell markers—FOXP1, SMARCA2." (PMID 36348001, 2022). "In all other tumour entities, no or only few GPR19-positive tumour samples were observed." (PMID 37923782, 2023).
GPR19 also shares sentences with these, for which no sentence is quoted: adenocarcinoma (1 paper); adrenal tumor (1); Anxiety (1); carcinoids of the lung (1); depression (1); Fanconi anemia (1); gastrointestinal stromal tumours (1); Hyperglycemia (1); melanoma (1); metabolic syndrome (1); pancreatic adenocarcinoma (1); papillary thyroid carcinomas (1); parathyroid adenomas (1); pheochromocytoma (1); Type 2 diabetes (1); urinary bladder cancer (1).